RETN (resistin)
Diseases named in the same sentence as RETN in open-access papers (continued):
Sharing a sentence is not in itself a finding about the gene and the disease.
periodontitis (39 papers, 2011 to 2026). An acute or chronic inflammatory process that affects the tissues that surround and support the teeth. "Since resistin has been linked to insulin resistance and periodontitis, it may hold promise as an inflammatory mediator." (PMID 38533160, 2024). "The periodontitis group demonstrated significant bone loss, an increase in the number of inflammatory cells and vascular structures, an increase in resistin expression and synthesis, and a decrease in the expression of adiponectin, leptin, and its functional receptor." (PMID 32410876, 2020). "A notable pathway RESISTIN, which could increase insulin resistance and susceptibility to diabetes, was found to be activated under periodontitis conditions, potentially linking periodontitis to T2D." (PMID 38811930, 2024). "In addition, triglycerides, total cholesterol, LDL-C, visfatin, resistin and leptin were significantly associated with periodontitis, indicating that these glycolipid metabolism mediators and these adipokines are crucial risk factors for the development of periodontitis." (PMID 37231396, 2023). "Measuring resistin levels in saliva offers an effective method to evaluate the impact of NSPT on obese individuals with periodontitis." (PMID 41602238, 2026). "Among adipokines, salivary resistin has been relatively less studied as a potential marker of systemic inflammation in obese individuals with periodontitis." (PMID 41602238, 2026). "Elevated resistin levels have been reported in individuals with periodontitis, suggesting its potential role as a pro-inflammatory adipokine contributing to periodontal tissue inflammation and disease progression." (PMID 41300847, 2025). "In a single-cell RNA analysis study involving 27 participants, researchers found that the resistin pathway was intensified in individuals with periodontitis and those with both periodontitis and diabetes." (PMID 40862144, 2025). "Other proteins that stand out are neutrophil defensin 1, annexin A1, lysozyme C, resistin, cathepsin G, myeloperoxidase, and azurocidin, which were upregulated between 2.8 and 25.1-fold in periodontitis." (PMID 40384977, 2025). "Following 4 weeks of therapy, TNF-α correlations intensified markedly with leptin (ρ = 0.671, P < 0.01), resistin (ρ = 0.619, P < 0.01), and periodontal indices (gingival bleeding index: ρ = 0.245; periodontitis grading: ρ = 0.331; P < 0.01)." (PMID 41244040, 2025). "In patients with periodontitis, alterations in the levels of various adipokines, such as adiponectin, leptin, visfatin, resistin and omentin-1, which condition periodontal healing and bone loss, have been studied." (PMID 38812668, 2024). "Based on the preceding findings, periodontitis patients with T2DM had greater levels of resistin in GCF." (PMID 38533160, 2024). "The aim of this study was to compare the effects of systemic antibiotics as an adjunct to NSPT with NSPT alone on periodontal clinical parameters and resistin levels in diabetic patients with periodontitis, to see which one improves the outcome of NSPT." (PMID 38533160, 2024). "Nonetheless, some potential biomarkers were noticed in the serum of patients with periodontitis, such as resistin, C-reactive protein, visfatin, oncostatin M, chemokine CXCL10, and proprotein convertase subtilisin/kexin type 9 (PCSK9)." (PMID 37535199, 2023). "A recent study identified that the expression of resistin in chronic periodontitis was significantly higher compared to the periodontal health group, and the level of resistin was also higher in the periodontitis patients with T2DM." (PMID 37664859, 2023). "Secondly, the gingiva mRNA expression of leptin, nampt/visfatin and resistin showed the maximum upregulation in the dual obese and periodontitis status, followed by in each single status, as compared with the control." (PMID 38069063, 2023).
periodontitis (continued). "Another study has shown that single-nucleotide polymorphism of resistin gene is correlated to the resistin levels in serum and GCF of diabetic patients with chronic periodontitis." (PMID 38149100, 2023). "Examining the expression pattern of the resistin-coding gene RETN in signal sender cells, RETN was most highly expressed in monocytes of the periodontitis group, but levels were significantly decreased after treatment, although it was not completely rescued." (PMID 36329504, 2022). "As in previous research, most RESISTIN transcripts were secreted by monocytes from healthy donors and patients with periodontitis." (PMID 36329504, 2022). "The neuropeptide genes ADM, IGF2, PDYN, and RETN were intersected between periodontitis and MDD, and FOSB was a crosstalk gene related to these neuropeptides on the transcriptomic level." (PMID 34721734, 2021). "Systematic and meta-analysis study reported high level of serum resistin observed in periodontitis patients as compared to healthy individuals." (PMID 32059714, 2020). "Following 2 months post-NSPT, greater reduction in resistin was observed in normal weight with periodontitis than obese periodontitis subjects." (PMID 32059714, 2020). "In accordance with our results, resistin has been observed in human gingival fibroblasts treated with Porphyromonas gingivalis and in gingival biopsies from gingivitis and periodontitis patients." (PMID 32410876, 2020). "NSPT is also expected to reduce the serum resistin level, which otherwise is present in higher amount in case of periodontal inflammation with periodontitis patients as compared to healthy individuals." (PMID 32059714, 2020). "Suresh and co-workers (2018) reported greater reduction in resistin which was observed in normal weight periodontitis than obese periodontitis at 8 weeks post-NSPT." (PMID 32059714, 2020). "A recent clinical study reported high levels of salivary resistin (14.45 ± 1.88 ng/ml) in normal-weight patients with chronic periodontitis compared to those with gingivitis (11.59 ± 1.6 ng/ml) and periodontally healthy cases (6.43 ± 0.81 ng/ml)." (PMID 29138754, 2017). "Many studies reported the detection of higher levels of resistin in the serum, gingival crevicular fluid, or saliva of patients with chronic periodontitis." (PMID 29138754, 2017). "In contrast to NAMPT and resistin, leptin and adiponectin expressions were significantly reduced in gingiva from periodontitis patients." (PMID 24707118, 2014). "In a Hisayama study of middle-aged women with moderate to severe chronic periodontitis done to determine the levels of circulating serum resistin and adiponectin, it was observed that patients with chronic periodontitis had increased serum resistin levels." (PMID 24692844, 2014). "The authors reported that serum resistin levels were higher in chronic periodontitis patients compared with the healthy counterparts." (PMID 24692844, 2014). "The authors concluded that periodontitis mainly influenced the circulating levels of resistin and adiponectin." (PMID 24692844, 2014). "In our previous study, it was observed that there were increased levels of serum resistin in periodontitis subjects compared with the control group, although this difference was not statistically significant." (PMID 24692844, 2014). "Furthermore, combining NSPT with SDD led to greater reductions in GI, PD, CAL, and GCF resistin in periodontitis T2DM patients compared to periodontitis T2DM patients who did not get SDD and periodontitis T2DM patients who received AZM with NSPT." (PMID 38533160, 2024). "Because resistin is a possible marker for inflammation and is influenced by inflammatory cytokines generated by periodontal pathogens in periodontitis, serum resistin levels in Group I were greater at one and three months compared to those in Groups II and III." (PMID 38533160, 2024).
periodontitis (continued). "The increasing level of resistin in obese patients and rats with periodontitis might be due to its ability to recruit TNF-α and IL-6." (PMID 38069063, 2023). "In addition, some scholars have also found that leptin and resistin have a certain impact on the pathogenesis of periodontitis." (PMID 37231396, 2023). "In addition, activated cell type-specific ligand-receptor interactions, including the BTLA, IFN-γ, and RESISTIN pathways, were prominent in patients with periodontitis." (PMID 36329504, 2022). "In addition, the proportion of RETN+ monocytes in the periodontitis group was twice that of the healthy controls, but decreased to levels similar to the healthy group after treatment." (PMID 36329504, 2022). "Therefore, GCF resistin levels is of interest as a potential incendiary marker for periodontitis with T2DM." (PMID 35574506, 2021). "In addition, as detected by IHC, a significantly (p < 0.05) enhanced number of resistin-positive cells was found in the furcation region of the periodontitis samples as compared to the control group." (PMID 32410876, 2020). "However, elevated resistin levels have been observed in serum and gingival crevicular fluid of periodontitis patients in clinical studies." (PMID 32410876, 2020). "Likewise, experimental periodontitis in rats resulted in the upregulation of resistin in gingival tissues and increased resistin protein production in the periodontium." (PMID 32410876, 2020). "Moreover, resistin seems to interfere with soft and hard tissue metabolism during periodontitis by reducing ALP activity and markers related to bone tissue and matrix formation." (PMID 32410876, 2020). "However, little is known about the explicit role of resistin in the etiopathogenesis of periodontitis." (PMID 32410876, 2020). "This high resistin level in the GCF during periodontitis could be explained by the quantity of PDL fibroblasts in addition to inflammatory cells, especially macrophages." (PMID 32410876, 2020). "Moreover, resistin seems to interfere with soft and hard tissue metabolism during periodontitis by reducing markers related to matrix formation and bone tissue." (PMID 32410876, 2020). "Karam and Al-Safi did not explore the periodontopathogenic bacteria in the saliva of the investigated cases; however, they assumed higher microbial content in the oral cavity of the cases with chronic periodontitis as a trigger for the local release of high levels of salivary resistin." (PMID 29138754, 2017). "The serum levels of resistin have also been observed to be elevated in people with periodontitis, indicating that it may also play a role in periodontitis." (PMID 26339142, 2015). "Chronic periodontitis being a low-grade infection is characterized by infiltration of the inflammatory cells within the periodontal tissues, which act as a source of production for resistin." (PMID 24692844, 2014). "However, further studies using specific resistin inhibitors and/or knockout animals could allow a better elucidation of the harmful role of resistin in inflammatory diseases such as periodontitis." (PMID 32410876, 2020). "Thus, the current evidence shows elevated levels of resistin, suggesting that this adipokine may play a role in the etiopathology of periodontitis." (PMID 32410876, 2020). "That the regulation of resistin in human and rodent periodontia might be similar is also supported by our findings which showed increased resistin expression in rat experimental periodontitis and elevated resistin levels in human PDL fibroblasts after exposure to a proinflammatory mediator." (PMID 32410876, 2020). "In this way, the author confirmed that resistin may be used as a marker of chronic periodontitis." (PMID 33202617, 2020). "Moreover, the expression of resistin was significantly increased in gingivitis and periodontitis." (PMID 24707118, 2014).
periodontitis (continued). "Four weeks after treatment, the correlations between TNF-α and leptin, adiponectin, resistin, FFA, the gingival bleeding index, and periodontitis grade were significantly greater (P < 0.05)." (PMID 41244040, 2025). "The synergistic impact of elevated pro-inflammatory cytokines (TNF-α, IL-6, and resistin) and reduced APN disrupts insulin signaling pathways, thereby affecting periodontitis." (PMID 41246338, 2025). "Previous studies have demonstrated that resistin and visfatin levels in GCF were elevated in patients with periodontitis compared to healthy controls, and decreased following NSPT." (PMID 40542868, 2025). "Using a Multivariate logistic regression model, periodontitis correlates to BMI, WHR, serum levels of triglyceride, total cholesterol, low density lipoprotein, and adipokines such as visfatin, leptin, and resistin." (PMID 37231396, 2023). "Therefore, resistin may play a role in the pathology of periodontitis." (PMID 32410876, 2020). "Clinical parameters of periodontitis, changes in serum resistin and periodontal pathogens in subgingival plaque were compared before and after NSPT in periodontitis subjects who were obese and with normal weight." (PMID 32059714, 2020). "Although most of our cases were periodontally healthy, salivary resistin levels in our obese cases whether diabetics (14.7 ± 2.8 ng/ml) or nondiabetics (14.4 ± 3.6 ng/ml) were close to the levels reported by Karam and Al-Safi in normal-weight patients with chronic periodontitis (14.45 ± 1.88 ng/ml)." (PMID 29138754, 2017). "However, the other study showed significantly higher levels of resistin in serum and gingival crevicular fluid in periodontitis with T2DM than in the chronic periodontitis group." (PMID 37664859, 2023). "Another evidence-based study conducted by the team found that periodontitis patients were presented with elevated levels of GCF or serum resistin, indicating resistin might be used as a potential biomarker for chronic periodontitis." (PMID 37884949, 2023). "Therefore, resistin as a potential mediator between T2DM and chronic periodontitis deserves more attention." (PMID 37664859, 2023). "Two studies showed comparable resistin levels in gingival crevicular fluid and serum between periodontitis with/without diabetics." (PMID 37664859, 2023). "It has been reported that resistin acts as a proinflammatory molecule by stimulating the secretion of tumor necrosis factor α (TNF-α), interleukin (IL)-6 and IL-12, thereby inducing its own production via a positive feedback cycle during periodontitis." (PMID 38149100, 2023). "In conclusion, although there was partial rescue in some cells that activated the RESISTIN signaling pathway, mDCs involved in periodontitis were not affected by non-surgical treatment and continued to activate RESISTIN signaling." (PMID 36329504, 2022). "Previous research showed that mean serum resistin was higher in obese subjects with periodontitis followed by non-obese periodontitis and non-obese healthy." (PMID 32059714, 2020). "Some studies have demonstrated elevated levels of resistin in the GCF of periodontitis patients compared to nonperiodontitis patients." (PMID 32410876, 2020). "It was observed that the resistin levels were higher while adiponectin levels were lower in periodontitis group compared to the nonperiodontitis groups." (PMID 24692844, 2014). "In a recent study done to determine the resistin levels in GCF of patients with chronic periodontitis and healthy controls, it was observed that there were significantly increased levels of resistin in chronic periodontitis compared with the healthy controls." (PMID 24692844, 2014). "Therefore, it is noteworthy that, unlike the preceding signaling pathways, treatment intervention did not rescue the changes in RESISTIN pathway activity due to periodontitis." (PMID 36329504, 2022). "However, the impact of NSPT towards serum resistin and periodontal pathogens was non-significant in those with periodontitis." (PMID 32059714, 2020).
periodontitis (continued). "Therefore, this study aimed to evaluate the effect of non-surgical periodontal therapy (NSPT) on salivary resistin levels in obese and non-obese individuals with generalized stage II grade B periodontitis, to emphasize the importance of oral healthcare in obese individuals." (PMID 41602238, 2026). "Furthermore, experimental periodontitis exacerbates inflammation not only by increasing the stromal vascular fraction (SVF) in AT to promote pro-inflammatory cytokine (TNF-α and IL-6) secretion, but also by altering circulating levels of adipokines such as resistin, adiponectin, and leptin." (PMID 41246338, 2025). "Therefore, this study aimed to compare salivary resistin levels and periodontal parameters before and 12 weeks after non-surgical periodontal therapy (NSPT) in obese and non-obese individuals with generalized stage II grade B periodontitis." (PMID 41602238, 2026).